INS (insulin)
Diseases named in the same sentence as INS in open-access papers (continued):
Sharing a sentence is not in itself a finding about the gene and the disease.
Obesity (continued). "MiRNAs have been shown to regulate lipid metabolism, glucose metabolism, insulin secretion, and other obesity-related biological pathways, therefore finding key miRNAs by RNA-sequencing may uncover the mechanisms involved in improving metabolic syndrome and its comorbidities in bariatric surgery." (PMID 39010180, 2024). "Conversely, one previous study of 80 prepubertal euthyroid children with obesity revealed that TFQI was negatively associated with the Matsuda-index, demonstrating an association between decreased central sensitivity to THs and decreased whole-body insulin sensitivity." (PMID 39175570, 2024). "Thus, blocking cathelicidin could be a therapeutic strategy to reduce inflammation and improve insulin sensitivity in patients with obesity and MetS, paving the way for new treatments targeting AT inflammation." (PMID 39728453, 2024). "Interestingly, insulin hypersecretion have detected in patients with obesity as result of IR." (PMID 38599791, 2024). "Although the detailed mechanism by which SB affects the insulin signaling pathway remains unclear, future research addressing this aspect will contribute to a better understanding of SB-induced obesity and lifespan reduction, thereby significantly advancing our knowledge in this field." (PMID 39519584, 2024). "First, we investigated whether β-cell GHSR regulated insulin secretion under HFD-induced obesity." (PMID 38794702, 2024). "An increase in irisin concentrations in an obese state for a long period is a pathological condition and might be an adaptive compensatory response to hyperglycemia, although it finally results in potential irisin resistance, such as insulin and leptin resistance, which occurs in obesity." (PMID 39479712, 2024). "Additionally, lycopene improves insulin sensitivity by increasing the expression of glucose transporters (Glut1, Glut4) and reducing leptin levels, highlighting its role in improving both lipid and glucose metabolism in obesity models." (PMID 39519540, 2024). "Moreover, obesity itself may contribute to chronic low-grade inflammation and altered insulin signalling, promoting tumorigenesis." (PMID 38611106, 2024). "Similarly, in obesity, an increase in β-cell mass satisfies the elevated insulin demand." (PMID 39045459, 2024). "Moreover, the concomitant presence of proinflammatory signals activated in obesity, vasoconstriction induced by FFAs and decreased insulin-mediated vasodilation may also explain hypertension." (PMID 38133765, 2024). "However, whether body composition and body fat distribution can (partially) explain the distinct etiologies of the tissue-specific insulin resistant phenotypes in obesity, and whether this is different between men and women, is unclear." (PMID 38594756, 2024). "Moreover, several hepatic miRNAs, packaged inside EVs, could improve insulin sensitivity and stimulate pancreatic β-cell proliferation during obesity and insulin resistance, promoting compensatory islet hyperplasia." (PMID 38790954, 2024). "In addition, a recent 2024 study comparing the effects of a low-carbohydrate, high-fat diet with a Western diet rich in fats and sugars in male C57BL/6J mice further confirmed that the Western diet led to obesity, glucose intolerance, elevated insulin levels, and the onset of MASLD." (PMID 39796579, 2024). "Significant weight regain following bariatric surgery may lead to the deterioration of metabolic improvements achieved through the procedure, including increased insulin resistance, reemergence of diabetes, worsening nonalcoholic fatty liver disease, and recurrence of obesity-related comorbidities." (PMID 39420888, 2024). "Finally, the endocannabinoid system has been shown to mediate the effects of the IM on mucosal permeability and may also play a key role in the regulation of insulin and obesity." (PMID 38474087, 2024).
Obesity (continued). "First, inflammatory markers and insulin levels were not measured, which could have provided additional insights into the underlying mechanisms of the joint effect of obesity and metabolic disorders on fatty liver." (PMID 38918729, 2024). "It is hypothesized that obesity causes metabolic abnormalities such as hypertension, glucose metabolic disorders, and dyslipidemia due to uncontrolled FFA release from adipose tissue and decreased insulin sensitivity." (PMID 39377071, 2024). "Besides exacerbating the hormonal alterations induced by pregnancy and affecting insulin release, obesity can also increase pro-inflammatory cytokines characteristic of the pro-inflammatory profile of pregnancy, inducing the dedifferentiation of β-cell and decreasing the insulin secretory activity." (PMID 39083072, 2024). "Relevant to obesity, evaluation in mouse models have indicated that the combination of dasatinib and quercetin reduces inflammation, alleviates metabolic dysfunction pre-adiposity, and facilitates the differentiation of adipose cells into mature, insulin-responsive ones." (PMID 38812556, 2024). "Our findings show that, on a high-sugar diet that induces obesity-like phenotypes, including insulin resistance, interorgan communication between muscle, neuronal, and fat tissue maintains insulin production and adipose insulin sensitivity, which mitigates sugar-induced hyperglycemia." (PMID 39033139, 2024). "Additionally, P4 CFS increased adiponectin expression, enhancing insulin sensitivity, glucose uptake, and fatty acid oxidation, which could protect against obesity-related complications." (PMID 39767692, 2024). "However, obesity may further decrease insulin sensitivity, which impairs glucose uptake and elevate plasma FFA levels." (PMID 39083072, 2024). "The lipid-handling disorders and cardiovascular diseases were deemed more complex because not everything in them could be related to insulin function and control (including the elusive primeval causes of obesity)." (PMID 38396928, 2024). "In addition, it remains unclear which exercise approach is the best; however, aerobic exercise is highly effective in improving insulin sensitivity in children and adolescents with obesity." (PMID 39337980, 2024). "Lifestyle modifications classically recommended in patients with obesity represent a significant challenge in the clinical routine management of patients with T1D, given the difficulties in managing hypocaloric diets and physical activity in insulin-dependent patients." (PMID 38642584, 2024). "The excessive fat accumulation in obesity is caused by an energy imbalance that generates signalling through the TNF family cytokines that mediate cell death and inflammation within adipose tissue, eventually resulting in lipid leakage, glucotoxicity and insulin resistance." (PMID 38248859, 2024). "Gene editing or specific inhibitors could be applied to our system to define the effects of adipokines such as adiponectin, leptin, resistin and omentin or metabolic and inflammatory pathways that impact hepatic insulin response in the setting of obesity and WAT inflammation." (PMID 39266553, 2024). "Interestingly, despite insulin resistance and decreased transport of insulin across the blood-brain barrier, the brain becomes more sensitive to the sympathoexcitatory effects and pressure action of insulin in obesity, through an unknown mechanism." (PMID 39963180, 2024). "Moreover, BCAAs may help decrease the incidence of obesity-related cancers by modulating metabolic pathways and improving insulin sensitivity." (PMID 39634548, 2024). "Moreover, hypoxia-inducible factor-1α, ethnicity, and gender are additional factors that may impact insulin sensitivity in children with obesity, particularly those with a family history of T2DM." (PMID 40302954, 2024).
Obesity (continued). "However, when hyperglycemia is corrected by the glucose-lowering agents, such as insulin therapy, insulin secretion is restored, a phenomenon known as release of “glucose toxicity,” and correction of insulin resistance factors such as obesity also improves insulin secretion." (PMID 39513056, 2024). "Consider the reason for this as overweight/obesity and IR through body compensation and lipolysis, forcing lipid transfer to hepatocytes and accumulation, abnormal lipid metabolism allows a sustained increase in free fatty acids in the body, impedes normal insulin secretion and IR." (PMID 39902164, 2024). "Thus, the underlying factors responsible for the obesity-mediated upregulation of myostatin remain to be elucidated but appear not to be mediated by ageing or insulin resistance per se." (PMID 37801203, 2024). "Among the metabolic factors related to liver fibrosis, obesity was the only factor that was significantly and independently correlated with liver fibrosis; this close relationship may be attributed to common pathophysiological insulin resistance mechanisms." (PMID 39775020, 2024). "The causal link between obesity and IR lies in the elevated levels of proinflammatory adipokines, such as IL-6 and TNF-α, released by adipose tissue following fat accumulation, which worsens tissue responses to insulin, thus resulting in T2D, dyslipidemia and hypertension." (PMID 38133765, 2024). "They only found obesity-induced mitochondrial destruction in type II muscle fibers, resulting in impairment of mitochondrial function, which may be one reason why an increased proportion of type II muscle fibers leads to insulin resistance." (PMID 36918975, 2023). "Additionally, Cer is involved in insulin signaling and metabolic disorders like obesity in humans." (PMID 37566018, 2023). "Moreover, poor diet and/or obesity can alter the gut microbiome and promote white adipose tissue expansion and metabolic dysfunction such as insulin resistance, which may impair cognitive function independently, and through systemic inflammation." (PMID 37371407, 2023). "Thus, obesity- or PA-induced dysregulation of ER and/or mitochondrial function results in a vicious cycle that aggravates mitochondrial and intracellular Ca2+ overload, leading to abnormal insulin action and metabolic alterations." (PMID 37524877, 2023). "The anti-obesity effects of indole-3-carbinol indole derivative were investigated in high fat diet-induced obese mice and were found to improve glucose intolerance, increase serum adiponectin concentration, and lower serum glucose, triacylglycerol, insulin and leptin concentrations." (PMID 37103396, 2023). "Rat insulin promoter (RIP25Mgn)-Cre;Lepr mice display hyperglycemia and reduced insulin secretion, but they also have high adiposity due to RIP-CreMgn activity in the brain; the disrupted glucose homeostasis is likely a secondary effect to obesity associated with loss of Lepr in the hypothalamus." (PMID 37850099, 2023). "Direct communication between the WAT and the pancreas may then participate in the β-cell expansion and increased insulin secretion observed at the beginning of metabolic disease and the ultimate β-cell failure characteristic of advanced states of obesity and T2D." (PMID 36768391, 2023). "Indeed, the cooperative contributions of major lifestyle-related factors, including obesity, physical inactivity, and insulinemic dietary pattern to insulin secretion and its metabolism, showed a remarkable relationship with NAFLD compared to EDIH as an alone dietary insulinemic score." (PMID 36670457, 2023). "In the setting of chronic longstanding obesity and hyperglycemia, it is plausible that a high enough insulin dose could overcome intrinsic immune cell IR to facilitate increased glycolysis and cytokine storm, though more studies are needed to assess this possibility." (PMID 36992811, 2023).
Obesity (continued). "Finally, in a clinical study, men with obesity and type 2 diabetes displayed increased prostate volumes, suggesting a link between enhanced adipose deposition, aromatase enzyme activity, high insulin levels and BPH." (PMID 36982560, 2023). "Our findings suggest that obesity, hormones, and maternal inheritance may be involved in the selection of males, but not females, who have risk alleles involved in insulin production for the early development of T2D." (PMID 37291636, 2023). "In sum, induction of T2DM and obesity increased tissue egg counts, mature egg percentage, and fibrosis density, while schistosome infection induced changes in the lipid profile and blood glucose levels in infected diabetic and obese groups and impacted favorably insulin levels in obese mice." (PMID 37296126, 2023). "The authors further discussed that the high odds of overweight and obesity in this population may be attributed to the weight-gaining side effects of certain medications, specifically thiazonlinedione and sulphonylureas when coupled with insulin." (PMID 36821504, 2023). "However, AEDT appears to be the most effective strategy for increasing insulin sensitivity with or without weight loss compared to aerobic or diet alone among populations with overweight/obesity." (PMID 38049873, 2023). "However, the observed anabolic and mitogenic effects of insulin on the adrenal cortex have led to the hypothesis suggesting a potential two-way relationship between obesity and AIs." (PMID 37510727, 2023). "Furthermore, its affected promoter may reduce this ability, therefore correlating with obesity and an increased plasma insulin concentration." (PMID 37763073, 2023). "Furthermore, ieIRKO mice show markedly increased HCC on long-term HFD feeding, suggesting that impaired insulin signaling, such as insulin resistance, in the gut plays a key role in the development of naturally-occurring HCC associated with obesity and an unhealthy diet." (PMID 37852976, 2023). "In women, obesity reduces female fertility and increases offspring obesity; a high maternal BMI may increase the birth and childhood weight due to the elevated maternal glucose and insulin concentrations, which drive foetal growth and adiposity." (PMID 36904075, 2023). "Thus, MS assumes a prominent role in this scenario, as it is a syndrome that is strictly related to obesity, especially the one characterized by the accumulation of fat in the abdominal region, which contributes to increased insulin resistance and cardiovascular diseases." (PMID 37510560, 2023). "In this way, our current data suggest that, even in the background of obesity and aging, long-term exercise could induce relevant adaptations in iWAT that may have accounted for the beneficial effects on glucose homeostasis and insulin resistance." (PMID 37204588, 2023). "While it has been reported that insulin resistant skeletal muscle shows an accumulation of fatty acyl‐CoAs, the role of the enzymes which catalyze their synthesis is still sparsely studied in human muscle, in particular the influence of obesity, and insulin resistance." (PMID 37726199, 2023). "In addition to insulin-sensitizing therapeutics like pioglitazone, the recent repurposing of other type 2 diabetes medications for weight management heralds a new optimism for obesity treatment." (PMID 37402955, 2023). "Obesity has been long established as an independent risk factor for CVD and is known to be linked to risk factor clustering, likely due to the buildup of excess adiposity augmenting several pro-inflammatory states, including decreased insulin sensitivity and adipocyte tissue dysregulation." (PMID 37835084, 2023). "Consequently, the compensatory increased insulin levels in insulin resistant states (including obesity) stimulate the SREPB-1c and increase expression and activity of all three desaturases, which was confirmed by studies in streptozocin induced diabetic animals." (PMID 37545582, 2023).
Obesity (continued). "Thus, our findings suggest that CCN3 may serve as a potential therapeutic target for improving insulin sensitivity and preventing obesity in CAD patients." (PMID 37919772, 2023). "Thus, in patients with obesity and sarcopenic obesity, muscle quality was positively associated with insulin sensitivity per se, irrespective of the presence of fatty liver." (PMID 36831008, 2023). "Increasing evidence suggests that obesity-related insulin/IGF signaling pathways may promote invasion and metastasis, three of the ten characteristics of cancer, by maintaining proliferative signaling, evading apoptosis (or fighting cell death), and sustaining proliferative signaling." (PMID 37764823, 2023). "Recently, we reported that excess intracellular Ca2+ induced by obesity tightly binds with plasma membrane phosphoinositides (PIPs) to form Ca2+-PIPs, which blocks the membrane targeting of various pleckstrin homology (PH) domains and disrupts insulin signaling." (PMID 37121975, 2023). "In addition to their effects on insulin and leptin, polyphenols have been shown to exert anti-obesity by directly modulating neuropeptides in food intake, as anthocyanins were reported to inhibit neuropeptide Y, suppressing obesity in high-fat diet-fed rats." (PMID 36829976, 2023). "When applied concurrently to mouse striatal slices, the effect of insulin plus leptin on evoked [DA]o is not additive, suggesting the elevated leptin levels that accompany obesity might also contribute to the loss of brain InsR sensitivity in this state." (PMID 36979453, 2023). "Thus, when obesity- and lipid-related abnormalities are present, the reduction of TT and E2 suggests the possible presence of insulin resistance in neurons of the HPG axis, whereas the role of aromatase may not be significant." (PMID 38260153, 2023). "This may explain the dual relationship between osteocalcin and preptin reported in the literature: while preptin co-secreted with insulin stimulates osteocalcin production, the hyperleptinemia seen in obesity may counteract this mechanism and downregulate serum osteocalcin." (PMID 37755271, 2023). "In addition, significant decreases were observed in oxidative stress level, insulin/mTOR/cell growth and proliferation, and in leptin/PI3K-Akt-mTORC1 pathways, which are implicated in obesity-related conditions such as diabetes, cardiovascular diseases, and cancer." (PMID 37047134, 2023). "Obesity is related to an increase in the secretion of leptin-a key adipokine for maintaining the body’s energy homeostasis (stimulating satiety and tissue sensitivity to insulin), which also, among others, regulates the tone of the vascular walls and reproductive functions." (PMID 36979669, 2023). "In summary, the identified DEPs have diverse biological functions that may influence the susceptibility to and perpetuation of the metabolic syndrome in individuals with obesity including inflammation, tissue remodeling, glucose and lipid metabolism, pancreatic function and insulin secretion." (PMID 38092892, 2023). "In addition, our follow‐up investigation indicated that bariatric surgery improved microvascular status of patients with obesity, and baseline blood pressure as well as fasting insulin were independent predictors of retinal vascular benefit 6 months after surgery." (PMID 36872300, 2023). "Additionally, obesity-induced decreased insulin sensitivity may lead to an impaired olfactory perception of fats, leading to disinhibited eating." (PMID 36409650, 2023). "However, when individuals engage in long-term training at moderate intensity (at 40–50% of maximum power), this leads to a reduction in body fat, improves its oxidation, and therefore acts on insulin concentration levels, making it well tolerated by people suffering from obesity." (PMID 37508677, 2023).